EPCAM (epithelial cell adhesion molecule)
Diseases named in the same sentence as EPCAM in open-access papers (continued):
Sharing a sentence is not in itself a finding about the gene and the disease.
tumor (continued). "Median TIS in the tumor bed was respectively 0 (range 0–12) for CEA, 0 (range 0–12) for EpCAM, 6 (range 0–12) for αvβ6, and 1 (range 0–12) for uPAR." (PMID 33799475, 2021). "For example, immunomagnetic CTC enrichment based on epithelial cell adhesion molecule (EpCAM) had used to be FDA-approved method, but it can't find tumor cells that lose EpCAM expression because of epithelial-mesenchymal transition (EMT)." (PMID 34976053, 2021). "CEA, EpCAM, and αvβ6 expression was significantly lower in the tumor bed compared with adjacent pre-existent mucosa (p < 0.01 for CEA, EpCAM, and αvβ6)." (PMID 33799475, 2021). "Additional studies have shown increased tumor control in vivo with combinations of radiotherapy and IL-2 immunocytokines targeting CEA and EpCAM." (PMID 33803078, 2021). "Anti‐EpCAM CAR‐T cells were able to eliminate PC3M cells which express high levels of EpCAM in vivo and in vitro, as well as able to inhibit the tumour growth of PC3 cells that express low levels of EpCAM and prolong mouse survival in a PC3 metastasis model." (PMID 34585512, 2021). "To determine if soluble EpCAM can inhibit CTSL activity, we incubated recombinant EpCAM-Fc with tumor derived SKOV3 cell lysates as a source of CTSL (SKOV3 cells have the highest CTSL activity in the panel of tested cell lines)." (PMID 33980181, 2021). "Some CTECs in different types of carcinoma patients were found to express a variety of tumor and mesenchymal markers, such as HER2, PD-L1, EpCAM, CD44v6 and Vimentin." (PMID 32599893, 2020). "The number of EpCAM+ CTCs was decreased significantly after operation, and all the patients with CTC reduction showed tumor remission." (PMID 32610709, 2020). "Clinically, circulating tumor cells (CTCs) that underwent EMT serve as a prognostic marker of a metastatic spread and can be isolated from patient’s blood using epithelial cell adhesion molecule (EpCAM) as a cell surface marker." (PMID 32121660, 2020). "Tumor cells in metastases also strongly expressed the mesenchymal markers smooth muscle actin (SMA/ACTA2) and nuclear TWIST, while EPCAM expression was weaker compared with tumor cells in spheroids." (PMID 32533757, 2020). "BCSCs have been isolated from tumor samples and breast cancer cell lines using a combination of surface markers such as CD44, CD24, EpCAM, CD133 and ALDH, among others." (PMID 32183150, 2020). "In vitro studies suggest that M hyorhinis infection promotes tumor progression in HCC patients, by increasing the migratory capacity of HCC cells, through the interaction of p37 with epithelial cell adhesion molecule (EpCAM)." (PMID 32075244, 2020). "IHC-P analysis of tumors from EpCAM+ NASH animals further confirmed significant higher EpCAM, β-catenin, Ki-67, and Vimentin, thus suggesting that HCC tumor growth in NASH animals by EpCAM-expressing Hepa1-6 was highly tumorigenic." (PMID 32547703, 2020). "CellSearch identifies circulating epithelial tumor cells, defining the CTC phenotype as EpCAM+ (Epithelial cell adhesion molecule), Cytokeratins (8+, 18+, and/or 19+), DAPI+ and CD45−, and only counts intact cells (intact cell >4 microns)." (PMID 33597950, 2020). "To overcome these limitations of EpCAM, we decided to test CD147, CA9, and CD70 as potential tumor markers for ccRCC." (PMID 33276608, 2020). "We have examined the four different tumor cell lines and tumor samples from patient and revealed that the SERS response in our optofluidic device correlates with the level of EpCAM expression established by immunocytochemical analysis." (PMID 33182636, 2020). "CTCs consist of epithelial cells (high-EpCAM), low-EpCAM cells, EMT cells, circulating tumor stem cells (CTSCs), and hybrid EMT/MET cells." (PMID 33339353, 2020). "In same tumor model, lnc-DILC expression in CD24+/EpCAM+ hepatic CSCs connects hepatic inflammation with liver CSC expansion, with low lnc-DILC levels to be predictive of early tumor recurrence and poor patient survival rates." (PMID 32932969, 2020).
tumor (continued). "Expressions of CD90, EpCAM, CD133, CD24, SOX9, CD44, CK19, and CD47 were positively related to immune infiltration level in HCC, negatively related to tumor purity." (PMID 32184801, 2020). "Various CARs have been engineered into NK-92 cells to kill specifically CD19, EpCAM, or CD33-positive tumor cells, and these CAR-NK cells have shown high anti-tumor effects." (PMID 33193399, 2020). "In studies aiming to quantify all tumor-derived cells in the bloodstream, GAS2L1 should therefore be combined with other markers such as EPCAM." (PMID 33333841, 2020). "Later, plasma membrane-bound HSP70 was proposed to be used as a specific easily detectable marker of CSC-like circulating tumor cells that have undergone EMT and consequently lost the epithelial cell surface markers EpCAM and CD326." (PMID 32268506, 2020). "We have shown that simultaneous treatment of animals with anti-EpCAM fusion toxin based on LoPE and HER2-specific liposomes loaded with Bn leads to concurrent elimination of primary tumor and metastasis." (PMID 33081407, 2020). "Pathological staining showed that the tumor stem cell markers (CD133 and EpCAM) were both highly expressed in recurrent samples compared with initial tumor samples (CD133+: 19 vs. 5%, p = 0.002; EpCAM+:15 vs. 6%, p = 0.005)." (PMID 32983980, 2020). "We analyzed orthotopic tumors in EpCAM+ group NASH animals by IHC-P and compared them with adjacent non-tumor liver." (PMID 32547703, 2020). "Immunohistochemical staining with antibodies against EPCAM and KI67 show that the effect on proliferation is mainly localized in the tumor cell population of these co-cultures." (PMID 33103995, 2020). "Another important observation was that the amount of tumor-specific EVs (enriched using tumor-specific markers anti-EGFR, anti-MAGEA3, anti-EpCAM, and anti-CSPG-4) varied among different patients." (PMID 33158181, 2020). "At 3 weeks post-injection we isolated from tumor xenografts EpCAM+/PKH26+ and EpCAM+/PKH26− cells that were used for further characterizations." (PMID 31910865, 2020). "Compared with the traditional 2D cultured tumor cells (2D-HepG2), 3DP-HepG2 showed significantly improved expression of tumor-related genes, including ALB, AFP, CD133, IL-8, EpCAM, CD24, and β-TGF genes." (PMID 32582546, 2020). "We strongly believe that PIM-1 overexpression in EpCAM(+) CTC fraction merits to be further evaluated and validated as a non-invasive circulating tumor biomarker in a large and well-defined patient cohort with mCRPC." (PMID 32397108, 2020). "The C649T, C1467G and T488C + G791A + G2153A mutations are loss-of-function mutations, which inhibit the transport of extracellular matrix proteins, such as EPCAM and CD9, thereby attenuating cell adhesion and promoting tumor metastasis." (PMID 32123160, 2020). "Cell samples were enriched for tumor cells and EOC origin was confirmed by intracellular staining of CK7, surface staining of CA125 and EpCAM, and HE4 gene expression." (PMID 33346216, 2020). "In HCC, several studies have shown that EpCAM is enriched in CSCs of HCC origin and that EpCAM-expressing HCC cells share more stem cell characteristics, have greater invasive, as well as tumor formation ability compared with EpCAM-negative cells." (PMID 32391048, 2020). "MPs positive for AnnexinV, EpCAM, and ASGPR1 decreased 7 days after curative R0 tumor resection, suggesting close correlation with tumor presence." (PMID 31935901, 2020).
tumor (continued). "Tumor EVs often contain oncogenic proteins such as EGFRvIII, EGFR, heat shock proteins (HSP), CD326/EpCAM, and KIT." (PMID 32260433, 2020). "Furthermore, EpCAM-specific antibodies were conjugated with bouganin (citatuzumab bogatox), Pseudomonas exotoxin A (oportuzumab monatox) and alpha-amanitin, with interleukin-2 to activate T cells in the vicinity of EpCAM-positive tumor cells (huKS-IL2), and with encapsulated inhibitory RNAs." (PMID 32507912, 2020). "Although PC3 express low levels of EpCAM, anti-EpCAM CAR cells were able to inhibit the tumor growth of PC3 cells and to prolong the animal survival." (PMID 32391048, 2020). "In this study, we also found that high levels of soluble CD44, CD44v6, CD44v8-10 and EpCAM were correlated with elevated levels of CA19-9, suggesting that their expression is involved in tumor progression." (PMID 32039729, 2020). "In contrast to EpCAM, CA9, CD70, and CD147 represent promising tumor-specific biomarkers for EVs in ccRCC." (PMID 33276608, 2020). "Epithelial cell adhesion molecule (EpCAM) and Prominin 1 (CD133) are frequently used to identify Huh-7 human HCC TICs as NOD/SCID mice developed tumor after receiving Huh-7 cells expressing these two antigens." (PMID 31366337, 2019). "In tumor cells, deletion of the RGD motif resulted in a mild reduction in transduction efficiency with EpCAM-retargeted virus in A-431 cells and a moderate reduction in MCF-7 cells." (PMID 31811202, 2019). "Recent research confirms that therapeutic strategies, using EpCAM/CD3-bispecific antibody, are significantly effective in tumor elimination." (PMID 31354723, 2019). "Remarkably, in this 3D set-up, the transduction efficiency of targeting to the original receptor (i.e. CAR) resulted in comparable numbers of transduced tumor cells as with EGFR- and EpCAM-retargeted viruses." (PMID 31811202, 2019). "We further confirmed that tumor/immune cell mixture was preserved after digestion by immunofluorescence microscopy for CD45 and EpCAM." (PMID 31196138, 2019). "Following fixation and permeabilization, epithelial cell adhesion molecule EpCAM+/FVD−/CDX2high and EpCAM+/FVD−/CDX2low tumor cells were double-sorted, and total RNA was extracted from two patient-derived xenografts (PDXs) and one spheroid sample." (PMID 31783700, 2019). "We characterize the phenotype of EpCAM+ CD4+ T cells as PD-L1+ CCR5+ CCR6+ and further confirm that this subset also increases in tumor microenvironments with irregulated p38 MAPK signaling pathway." (PMID 31354723, 2019). "A phase I clinical trial evaluated the safety of intra-tumor injection of VB4-845, an immunotoxin targeting epithelial cell adhesion molecule (EpCam), in 20 patients with squamous cell carcinoma of the head and neck (SCCHN)." (PMID 30621280, 2019). "CTC analyses by CellSearchTM (a FDA‐cleared platform for clinical testing of EpCAM+ CTCs) of these CDX models demonstrated an increased number of CTCs and tumor burden in the later generations of CDX mice." (PMID 31216110, 2019). "They showed a higher recovery of EpCAMlow tumor cell using SCLC cell lines with high and low EpCAM expression and a higher CTC count using the label-independent Parsortix device compared to the EpCAM-based CellSearch system in all 12 patients’ samples." (PMID 31212989, 2019). "The typical mPDAC markers, e.g. EPCAM, cytokeratin 19, CD133 etc., were indeed enriched in these cells, validating the tumor cell identity." (PMID 30799483, 2019). "Currently, EpCAM+CTCs have been intensively investigated in HCC, although the knowledge about their clinical relevance in HCC is lagging behind other major tumor types, such as breast cancer, prostate cancer and lung cancer." (PMID 31269959, 2019).
tumor (continued). "Intriguingly, a CD26+ circulating tumor cell (CTC) population that is CD44+ and CD66c+ but EpCAM− and CD133− is an independent prognostic factor for CRC recurrence." (PMID 31285270, 2019). "Expression of SS-induced genes, such as Early growth response 1 (Egr1), Activator protein 1 (Ap1), Epithelial cell adhesion molecule (Epcam), and Kruppel-like factor 8 (Klf8), were the highest in the circulating GFP+ tumor cells." (PMID 30651129, 2019). "Along with the protein depletion confirmed by the immunochemistry assay, we confirmed the loss of expression of MLH1 at the RNA level, as well as the upregulation of EPCAM and TFF3 in tumor cells, which are known to be overexpressed in cancer cells." (PMID 31829268, 2019). "Both EpCAM+/Vim-GFP+ and EpCAM−/Vim-GFP+ tumor cells were detected in circulation, exhibited stemness properties, and were much more invasive compared to epithelial tumor cells." (PMID 30934773, 2019). "Subsequently, colony formation and tumor sphere assays revealed significant decreases in CFUs for CD24, CD133, EpCAM, and E-cadherin shRNA knockdown clones compared to sheGFP controls (P < 0.05)." (PMID 30467381, 2019). "The results of IF staining show the EpCAM expression and CD4+ T cells distribution in tumor tissues and their para-cancerous tissues of CC patients." (PMID 31354723, 2019). "A central player in the tumor microenvironment proved to be the CSCs which can be marked by CD133, CD44, CD90, EpCAM, and CD105." (PMID 31781608, 2019). "Of note, the mammary epithelium-like structure with differentiation markers (both EPCAM and TP63) was observed in the xenografts generated by tumor sphere cells." (PMID 31196164, 2019). "We selected two tumor co-culture cell models, using EGFR and EpCAM as targetable receptors on tumors." (PMID 31811202, 2019). "Tumor cells showed high rates of CD133 and EpCAM expressions with 85.8±0.8 and 85.1±0.4, respectively." (PMID 31057717, 2019). "As shown by double immunofluorescence analysis with anti-EpCAM, anti-CD44, and anti-human CD133/1 antibodies, we observed that SDC1 was accumulated in tumor cells with CSC properties." (PMID 31443604, 2019). "CTCs were enriched from 50 mL whole blood and identified via fluorescence microscopy detecting EpCAM and/or CEA tumor marker expression." (PMID 31134762, 2019). "In vitro studies demonstrated the superior ability of FcαRI to induce neutrophil-mediated tumor cell killing for multiple tumor antigens, including EGFR, HER2, EpCAM, HLA-II, CD20, CD30, and carcinoembryonic antigen." (PMID 30984170, 2019). "Here, we showed that VDAC1 silencing in A549 cell-derived tumours resulted in reduced expression of lung-specific CSC markers, such as ALDH1, KLF4, SOX2, CD133, CD44, CD144, EPCAM, Oct3/4 and Nanog." (PMID 30544833, 2018). "Because OPN plays a crucial role in tumor progression and metastasis through binding to CD4444,45, we compared the levels of OPN and the capacity for HCV replication in EpCAM+/CD44+ CSCs and EpCAM−/CD44− cells." (PMID 30177680, 2018). "Jahchan and coworkers have isolated and characterized a population of long-term tumor-propagating cells in a mouse model of SCLC; this population is characterized by high levels of CD24 and EpCAM expression and was identified also in primary human SCLCs." (PMID 30060526, 2018). "In HCC, EpCAM emerged as an important CSC surface marker and EpCAM+ cells correlate with worse prognosis and possess CSC-like properties showing tumor-initiating capabilities with as few as 200 cells in a nude mouse model." (PMID 30075764, 2018). "Significant correlation rates between PDX rate and patient’s prognosis, tumor stage and stem cell markers (CD133+CXCR4+EpCAM−) was observed." (PMID 30060526, 2018). "B Gating strategy for circulating tumor cells (CTCs) after EpCAM enrichment CTCs were identified as nucleated, viable CD45-EpCAM+ cells." (PMID 30514390, 2018). "Moreover, the EpCAM antigen could be used to detect circulating tumor cells." (PMID 30112355, 2018).
tumor (continued). "Bispecific CD44-EpCAM aptamer suppressed intraperitoneal tumor outgrowth more significantly than individual CD44 and EpCAM aptamers did alone or in combination through enhanced targeting of cancer cells." (PMID 29562664, 2018). "Flow cytometry analysis of sorted single cells allowed us to first compare surface expression of EPCAM and ECAD protein on matched CTCs, tumor cells, and WBCs." (PMID 29568081, 2018). "In a more recent work, Choi and coworkers showed that vaccines based on DCs pulsed with EpCAM peptides elicit a strong antigen-specific CTL response and result in a significant suppression of tumor growth in a mouse model." (PMID 30200242, 2018). "Overall, the ratio of PC-3-EpCAM-KD tumour volumes decreased faster in response to DTX, compared to PC-3-EpCAM-scr group (P < 0.01), suggesting that the KD of EpCAM can increase the DTX sensitivity of CaP tumours in s.c. mouse model." (PMID 30419852, 2018). "In this study, we analysed the association between clinicopathological characteristics of HCC patients and tumour expression of four HPC markers, EpCAM, NCAM, CK19, and DLK1." (PMID 29774107, 2018). "For this, cancer cells were enriched and detected using the CellSearch system that first enriches them by magnetic capture after anti-EpCAM ferrofluid labeling and visualizes cytokeratin-positive, CD45-negative tumor cells." (PMID 29721166, 2018). "In the case of MDA-MB-231-derived tumours treated with si-hVDAC1, the expression of ALD1HA1, KLF4, SOX2, CD133 and EPCAM were highly reduced, again as analysed by IHC, immunoblotting or q-RT-PCR." (PMID 30544833, 2018). "In this study, the EpCAM-targeting aptamer was conjugated to a DY647 fluorophore and injected intravenously into the tumour bearing mice." (PMID 30586898, 2018). "To investigate this, we analyzed the correlations between well-known immune and tumor cell markers (CD45 or PTPRC, CD3, CD8, etc and CDH1, EPCAM) with ISGF3 subunits within the TCGA dataset." (PMID 30355451, 2018). "With this strategy, more heterogeneous CTCs, including EpCAM+/FRα−/low, EpCAM−/low/FRα+, and EPCAM+/FRα+ tumor cells, can be captured." (PMID 29352248, 2018). "To confirm the activation of lymphocytes by EpCAM peptide-stimulated DCs, we investigated the levels of IFN-γ secreted by T cells following stimulated with tumor antigens." (PMID 29298343, 2018). "Tumor tissue from the EpCAM peptide-CTL group showed weak expression, as determined by immunohistochemical staining of EpCAM." (PMID 29298343, 2018). "In order to isolate tumor-initiating cells (TICs) from HCC cells, we first evaluated the expression pattern of liver CSC markers (EpCAM, CD133, CD90) in SNU-398 and Huh7 cells." (PMID 29555987, 2018). "It is possible that EpCAM-, E-cadherin- and LGR5-carrying EVs participate to the preparation of the microenvironment to accommodate the subpopulation of tumor stem like cells originating from the LCC." (PMID 29137313, 2017). "We measured ∼14,000 tumour cells per ml of blood for mice injected with soluble TRAIL as compared with <3,000 tumour cells per ml for mice injected with EpCAM-targeted particles followed by treatment with soluble TRAIL." (PMID 28317839, 2017). "The expression level of CTLA4 only correlated with central tendency parameters, while expression of GLUL, FGFR4, tumour stemness markers KRT19 and EPCAM and immune checkpoint PDCD1 showed significant correlations with MRI heterogeneity parameters only." (PMID 28550313, 2017). "The tumour biopsies were fractionated into CD133+ and CD133−/EpCAM+ cells by immunomagnetic separation, confirmed by immunocytochemistry and Q-PCR." (PMID 28347289, 2017). "EpCAM, K19 or CD133 expression also showed a significant correlation with those of tumor stromal CD68 (+)/CD163 (+) TAMs and IL-6 (+) stromal cells." (PMID 28114366, 2017).